GSDME (gasdermin E)
Diseases named in the same sentence as GSDME in open-access papers (continued):
Sharing a sentence is not in itself a finding about the gene and the disease.
tumor (continued). "Surprisingly, we noticed that there was a positive correlation between CD8+T cells infiltration and GSDME expression and higher level of CD8+T cells predicted favorable RFS and OS of CRC patients, which suggested GSDME might influence the CD8+T cells in tumor microenvironment (TME)." (PMID 38853246, 2024). "Additionally, it was found that administering the synthetic FXR agonist GW4064 simultaneously with oxaliplatin could have a synergistic anti-tumor impact, as GW4064 enhanced the chemosensitivity of cells to oxaliplatin by inducing BAX/caspase-3/GSDME-mediated pyroptosis." (PMID 39062587, 2024). "Additionally, activation of gasdermin E (GSDME) could turn a “cold” tumor that was lack of immune response into a “hot” tumor that was controlled by the immune system." (PMID 36707884, 2023). "However, GSDME expression can modulate the quantity and function of tumor-infiltrating natural killer (NK) cells and CD8+ T lymphocytes, which triggers cytotoxic granule-mediated PFN-dependent killing and cytokine secretion, thereby enhancing the patients’ anti-tumor immunity." (PMID 37965452, 2023). "To verify this speculation, we screened tfRFP-B16 tumor cells with moderate or high expression of GSDME with green fluorescence protein (GFP) or without GSDME expression, grouped as GSDME-GFPmidtfRFP-B16 cells, GSDME-GFPhitfRFP-B16 cells, and GSDME-/-tfRFP-B16 cells, respectively." (PMID 36438480, 2022). "Thus, we may observe an interesting phenomenon that tumor cells with low or no expression of GSDME underwent apoptosis after chemotherapies, while normal tissues with high GSDME expression may suffer from severe toxicity via caspase-3-mediated pyroptosis." (PMID 36209102, 2022). "In this study, we found that the pyroptosis genes including GSDMB, GSDME, NLRC4, NLRP2 and GZMA were hazardous genes in AML, and the genes of proinflammatory cytokines such as IL6 and TNF were found to be protective genes which maybe related with tumor microenvironment." (PMID 36553549, 2022). "Furthermore, a form of caspase-independent, GSDME-mediated cell death is described in “high-Gsdme” cancer cells, wherein granzyme B from NK and CD8+ T cells can enter via a perforin-dependent mechanism, cleaving GSDME and activating pyroptosis, with a consequent reduction in tumor growth." (PMID 35111698, 2021). "Previous studies have demonstrated that chemotherapy can induce pyroptosis through the cleavage of gasdermin E (GSDME), although many tumor cells show low or no expression of GSDME due to promoter methylation." (PMID 39667498, 2024). "More importantly, patients with low OTUD4 expression (biopsy III, IV) showed a lower level of GSDME, no significant upward trend of serum LDH concentration and a slower regression of the tumor than patients with high OTUD4 expression (biopsy I, II)." (PMID 36411454, 2022). "These siRNAs increased the response of human tumor cells to exogenous nucleic acids, induced pyroptosis and apoptosis in the presence of GSDME (Gasdermin E), but induced apoptosis in the absence of GSDME." (PMID 34195074, 2021). "GSDMA, GSDMC and PJVK are not detected in most human tissues (both tumor tissues and normal tissues), while GSDMB, GSDMD and GSDME are highly expressed in most human tissues (both tumor tissues and normal tissues), especially GSDMD." (PMID 34421915, 2021). "Besides, the knockdown of A20 could hardly induce the up-regulation of cleaved-Caspase 3, phosphor-MLKL or cleaved-GSDME in isolated xenograft tumors, indicating that cell death might not be involved in the effect of A20 on tumor progression both in vivo and in vitro." (PMID 32968045, 2020). "Hence, beyond the canonical and non-canonical pathways, the activation of GSDME is considered a promising approach to remodel the TIME and trigger durable anti-tumor immunity for cancer therapy." (PMID 39816682, 2025). "Hence, GSDME exerts its antitumor effect in SCLC through its interaction with the immune system, rather than by affecting tumor proliferation." (PMID 38169676, 2024).
tumor (continued). "Similarly, lobaplatin-induced pyroptosis is also converted into apoptosis in GSDME-knockout BALB/c nude mice, but this conversion does not affect its inhibition of tumor formation." (PMID 34522213, 2021). "Interestingly, in contrast to the reported mechanisms inducing pyroptosis in tumor cells,[23c] we found that granzyme B may induce hepatocyte pyroptosis by acting on GSDMD but not GSDME." (PMID 39494472, 2025). "Analysis of the tumor images, weights, and volumes revealed that the treatment efficacy significantly deteriorated with the use of the broad-spectrum caspase inhibitor Z-VAD, moderately decreased with the GSDME inhibitor, and did not significantly change with the other inhibitors." (PMID 41413917, 2025). "First, quantitative thresholds of pyroptosis component expression, such as caspase-3/8, GSDME, and NLRP3 may determine whether the net effect is anti- or pro-tumor, suggesting that fine-tuned modulation rather than binary activation/inhibition could optimize therapeutic impact." (PMID 41291696, 2025). "Compared to SIM alone, the extent of the inhibition was notably exaggerated when GSDME gene expression was promoted in the xenograft tissues by intake of DOX water by the mice, whereas switching on the GSDME gene expression per se did not affect tumour development." (PMID 35517821, 2022). "In addition, although GSDME has recently been shown to form pores in the plasma membrane when cleaved by caspase-39,11, this function occurs downstream of PCD pathways and does not explain its tumor suppressive activity." (PMID 30976076, 2019). "However, after GSDME was knocked down, the injection of SSZ with ID could no longer inhibit xenograft tumor growth." (PMID 30287942, 2018).
cancer (292 papers, 2012 to 2026). A tumor composed of atypical neoplastic, often pleomorphic cells that invade other tissues. "As discussed in "The role of pyroptosis in cancers" section, the DFNA5 gene encoding GSDME is frequently hypermethylated and silenced in multiple cancers, limiting the ability of caspase-3 to execute pyroptosis." (PMID 41291696, 2025). "And GSDME was up-regulated and activated by Tc3 in tumors, causing pyroptosis of cancer cells, consistent with the results of blood routine examinations of the mice." (PMID 39816682, 2025). "GSDME is regarded as a tumor suppressor gene, and it has been shown that many cancers harbor inactivating mutations." (PMID 40544161, 2025). "Previous studies have shown that loss of GSDME causes resistance to chemotherapy drugs in many cancer cells." (PMID 40103680, 2025). "In contrast to most other cancer types, where GSDME is either mutated or expressed at low levels, we found high expression levels of GSDME in patient samples and GB cell lines." (PMID 40544161, 2025). "To delve deeper into how GSDME cleavage is promoted in ULK1-deficient cancer cells, we performed qPCR and western blot analysis." (PMID 39215364, 2024). "Under specific scenarios, such as exposure to TNF-α, certain cancer treatment medications, or elevated levels of GSDME, caspase-3 can initiate GSDME-associated pyroptosis." (PMID 38304430, 2024). "While normal cells retain GSDME expression, many cancer cells epigenetically downregulate the GSDME expression, or harbor a mutated GSDME protein that results in loss of function." (PMID 38391959, 2024). "Subsequently, more studies have revealed that epigenetic inactivation, caused by methylation, leads to lower expression of GSDME in most cancer cells as compared to normal cells 33-35." (PMID 38169676, 2024). "One study found that 20 out of 22 gasdermin E mutations identified within cancer samples were associated with reduced pyroptosis in response to granzyme B." (PMID 35401556, 2022). "The roles of gasdermin E (GSDME), caspases, and related proteins associated with pyroptosis in cancer remain controversial." (PMID 34553845, 2022). "ROS which is the active form of oxygen has been shown to monitor apoptosis and autophagy in cancer cells and is associated closely with the caspase-GSDME pathway." (PMID 36119049, 2022). "The expression of Gasdermin E (GSDME) was linked with the cancer-associated fibroblast infiltration in multiple malignancies." (PMID 35432539, 2022). "Caspase-resistant cancer cells should be susceptible to this direct pathway, provided that the cancer cells express GSDME." (PMID 35673561, 2022). "GSDME epigenetic silencing and mutations resulting in loss-of-function have been reported in cancer tissues." (PMID 34335940, 2021). "The Gasdermin E (GSDME) signal pathway is activated, leading to pyroptosis of cancer cells and increased expression of damage-associated molecular pattern molecules (DAMPs), which in turn activate macrophages to release CRS-related cytokines." (PMID 33670734, 2021). "To establish the causal role of EMT in GSDME upregulation, we first attempted to induce mesenchymal transdifferentiation with transforming growth factor-β (TGFβ) in a variety of cancer cell lines." (PMID 34901025, 2021). "In order to thoroughly understand the mechanisms underlying GSDME regulation, we performed integrative bioinformatics analyses on publicly available pan-cancer datasets and discovered that EMT gene signatures were among the top correlates of GSDME levels." (PMID 34901025, 2021). "For example, a recent study suggested that GSDME-mediated cancer cell pyroptosis can cause cytokine release syndrome (CRS), a complication associated with chimeric antigen receptor (CAR) T cell therapy." (PMID 33406603, 2021). "In contrast, the inactivation of GSDME in the form of decreased expression instead of genetic mutation is associated with cancer." (PMID 34298833, 2021).
cancer (continued). "GSDME, a gene related to hereditary hearing loss, has been reported to be involved in various cancers in the past few decades." (PMID 34869364, 2021). "The expression of GSDME was statically associated with the cancer-associated fibroblast infiltration in diverse cancer types, such as BLCA, CHOL, GBM, KIRC, LIHC, MESO, STAD, and UCEC." (PMID 34381728, 2021). "Unfortunately, the role of GSDME in the cancer pathogenesis and underlying molecular mechanism deserve further investigation." (PMID 34381728, 2021). "Deafness, autosomal dominant 5 (DFNA5), which is known as GSDME in the context of cancer, is the fifth DFNA locus associated with ADNSHL." (PMID 33110423, 2020). "Recent results show that a number of cancer cell lines express sufficiently high levels of GSDME to cause pyroptosis upon treatment with apoptosis-inducing chemotherapy drugs." (PMID 32345661, 2020). "This was independently confirmed by others, and caspase-3-dependent cleavage of GSDME has been implicated as a mechanism underlying cancer cell response to several chemotherapeutics." (PMID 32340261, 2020). "These authors also showed that 20 of the 22 tested cancer-associated GSDME mutations reduce GSDME function, suggesting that GSDME inactivation is a strategy developed by cancer cells to escape immune attack." (PMID 32778143, 2020). "Blocking GSDME silencing in cancer cells makes them more susceptible to chemotherapy drugs; inversely, the toxicity of chemotherapy drugs to other tissues can be decreased by inhibiting GSDME." (PMID 30360387, 2018). "Furthermore, the application of paclitaxel activates caspase-3/7 in multiple types of cancer cells, thereby inducing apoptosis and activating GSDME to cause pyroptosis." (PMID 39584140, 2024). "In a study of 22 cancer-associated GSDME mutations, 20 were found to reduce GSDME function." (PMID 38553639, 2024). "Abnormal GSDME-mediated pyroptosis usually causes inflammatory diseases in cancer therapies." (PMID 38238307, 2024). "Overall, developing a more profound and enhanced knowledge of the role of GSDME-mediated pyroptosis in cancer may have substantial clinical utility as a diagnostic biological marker and provide novel strategies for preventing and treating tumors." (PMID 38104141, 2023). "For instance, interrogation of the TCGA database demonstrated that GSDME had a high prevalence of mutations, which were especially concentrated around the caspase-3 cleavage site; 20 of 22 cancer-associated GSDME mutations tested were shown to inhibit its function." (PMID 35592329, 2022). "Recent studies on GSDME were mainly reported in cancer cells, showing that GSDME could induce pyroptosis and cause cancer cell death." (PMID 35836195, 2022). "Owing to the important role of GSDMD/GSDME in the regulation of both pyroptosis and sensitivity to cancer therapy, a new role for pyroptosis may be implicated in the future." (PMID 36589680, 2022). "However, there are also various loss‐of‐function (LOF) mutations of GSDMD in different cancers, although this is less common than the epigenetic suppression of GSDME." (PMID 34459122, 2021). "Furthermore, TPL suppressed NRF2/SLC7A11 axis and synergized with erastin to kill both GSDME-expressing and GSDME-deficient cancer cells." (PMID 34108030, 2021). "Furthermore more, the induced expression of GSDME in cancer cell lines leads to decreased proliferation and suppressed colony formation, while GSDME deficiency contributes to the malignancy of tumors and drug resistance." (PMID 34298833, 2021). "Moreover, the level of GSDME expression has been linked to cancer patient outcome; a study showed that tumors deficient in GSDME developed drug resistance 5, and drug susceptibility was restored upon exogenous GSDME transfection in these cells." (PMID 34335940, 2021). "It remains to be seen if mice deficient in GSDME are more prone to developing cancer." (PMID 30976076, 2019).
cancer (continued). "Besides, genetic dynamics of GSDME may affect its function and be related with important physiological, as several cancer-related SNP mutations of HsGSDME cause loss-of-function (LOF)." (PMID 37134086, 2023). "In addition, GSDME expression is associated with good prognosis after chemotherapy in a variety of cancers and may be a potential prognostic biomarker." (PMID 37679782, 2023). "Therefore, GSDME-mediated pyroptosis may be one important cause of the severe side effects of cancer chemotherapy." (PMID 38016064, 2023). "This paradigm exploits the high basal expression or inducibility of specific gasdermins, particularly GSDME, in cancer cells." (PMID 41574659, 2026). "In cancer cells, pyroptosis is often induced by chemotherapeutic agents that activate caspase-3-mediated cleavage of GSDME." (PMID 40200299, 2025). "The expression of GSDME is of value in cancer progression and key to the efficacy of GSDME‐dependent pyroptosis." (PMID 40599236, 2025). "Pyroptosis is considered an immunogenic cell death, and GSDME overexpression in cancer cells has been shown to facilitate immune cell infiltration and to enhance antitumor immunity." (PMID 40645933, 2025). "Activation of the CASP3/GSDME signaling pathway can induce pyroptosis or apoptosis, which in turn affects the growth of tumors and the survival rate of cancer patients." (PMID 40695891, 2025). "Many therapeutic drugs trigger caspase-3-derived apoptosis, effectively eliminating cancer cells and laying the pivotal groundwork for pyroptosis as well, a process regulated by GSDME." (PMID 41291696, 2025). "By inhibiting DNA methylation, DAC upregulated GSDME expression, triggering caspase-3 cleavage and pyroptosis of cancer cells." (PMID 40698137, 2025). "A photocatalytic superoxide radical generation strategy enables the activation of light-controlled pyroptosis in cancer cells via the caspase-3/GSDME pathway, potentially facilitating the application of opto-controlled pyroptosis in cancer therapy." (PMID 40573305, 2025). "For example, it was found that the ROS/caspase-9/caspase-3 apoptotic pathway was activated by CAP exposure, leading to Gasdermin E (GSDME) lysis and cancer cell pyroptosis." (PMID 40649322, 2025). "Unfortunately, the GSDME gene is frequently hypermethylated in the promoter region in many cancer cell lines and primary tumors, significantly reducing its expression." (PMID 40432601, 2025). "It has been reported to increase the expression and activation of caspase-1 and GSDME in certain cancer cell lines, leading to membrane pore formation, release of immunostimulatory factors, and enhanced recruitment of immune effector cells." (PMID 40806716, 2025). "Our studies demonstrated that RG7388-induced pyroptosis was characterized by increased expression of cleaved GSDME, which can trigger cancer immune response." (PMID 40523886, 2025). "A major discovery was that the cleavage of GSDME by caspase-3 induces pyroptosis in certain GSDME-expressing cancer cells after chemotherapy, providing potential new approaches for cancer treatment." (PMID 40721578, 2025). "Given the established role of the PI3K-AKT pathway in cancer and its inhibition by docetaxel, We confirmed the phosphorylation of GSDME at S252 using western blot experiments." (PMID 41413917, 2025). "GZMB acts both directly on GSDME and indirectly via caspase-3, offering an alternative pyroptotic pathway in caspase-resistant, GSDME-expressing cancer cells." (PMID 40806716, 2025). "DAC is a DNA methyltransferase inhibitor, which is often used to upregulate the expression of GSDME and lyse caspase-3 to form a cytotoxic GSDME N-terminal, which triggers cancer cell pyroptosis." (PMID 40698137, 2025). "Analysis of TCGA data across cancers in proteinatlas.org showed that GSDME was expressed at higher levels in GB compared to other cancers." (PMID 40544161, 2025).